MMP9 (matrix metallopeptidase 9)
Diseases named in the same sentence as MMP9 in open-access papers (continued):
Sharing a sentence is not in itself a finding about the gene and the disease.
Arthritis (continued). "Indeed in our previous publications, we have shown that BC-associated metastasis is significantly augmented in mice with arthritis and that IL-17A, IL-6, COX-2, VEGF, MMP-9, IGF-II, M-CSF and TNF-α are all major players." (PMID 24674692, 2014). "Additionally, sPD-1 and MMP-9 expression was significantly reduced in the PD-L1-MSA group compared to that in the CIA group, and showed a strong correlation with the arthritis score and degree of joint swelling." (PMID 41451230, 2025). "Similarly, pharmacological inhibition of the LPA1 receptor by Ki16425 in the K/BxN serum-transfer arthritis model led to a reduction in arthritis severity by decreasing cartilage damage, bone erosion, and expression of RANKL, ITAC/CXCL11, Pro-MMP9, and MMP3, in mouse arthritic joints." (PMID 35408784, 2022). "MMP9, which inhibits both angiogenesis in the pannus and the activation of pro-MMP13 in SF, may play a pivotal role in the development of a MMP inhibitor and therapeutic drug for arthritis." (PMID 35329213, 2022). "In addition, the expression of other MMPs, such as MMP-2, MMP-3, and MMP-9, is elevated in arthritis, and these enzymes degrade non-collagen matrix components of joints." (PMID 34209006, 2021). "MMP2, MMP9, and EMMPRIN are members of the MMP protein family and are involved in breakdown of the extracellular matrix in normal physiological processes, such as reproduction, embryonic development, and tissue remodeling, as well as in disease processes, such as arthritis and metastasis." (PMID 25928011, 2015). "According to a study of adjuvant-induced arthritis in rats’ synovium, inhibition PPAR-γ expression by T0070907 or PPAR-γ siRNA could significantly promote the proliferation of fibroblast-like synoviocytes and expressions of c-Myc, Cyclin D1, MMP-1, and MMP-9, except for TIPM-1." (PMID 33397492, 2021). "Our test showed the serum levels of MDC and MMP-9 were decreased in patients with renal damage than those without the damage, and the serum level of MDC was markedly decreased in patients with arthritis than those without the damage." (PMID 26430407, 2015). "In psoriasis, CCL4, GZMK and KLRF1 show significantly higher, while ADM, ANXA3, IL4, MMP9 and OLR1 show significantly lower expression levels in patients with arthritis negative psoriasis compared to patients with symptoms of arthritis." (PMID 20444268, 2010). "In a previous study, genetic ablation of MMP-2 resulted in an exacerbated level of collagen antibody-induced arthritis, while the lack of MMP-9 attenuated it compared to the wildtype mice indicating suppressive role of MMP-2 and pro-inflammatory role of MMP-9 in the process." (PMID 30949048, 2019). "Indeed, knockout mouse experiments revealed that the absence of MMP-9, but not of MMP-2, reduces arthritis progression." (PMID 19664212, 2009).
dry eye (106 papers, 2009 to 2026). "MMP-9 is an inflammatory molecule that has a role in the mechanisms of dry eye associated with Sjögren’s syndrome." (PMID 40597071, 2025). "An immunoassay kit has been developed to detect elevated tear MMP-9 levels, showing good diagnostic performance and correlation with dry eye severity." (PMID 39797282, 2025). "The purpose of this study was to compare the expression of MMP-9 in dry eyes treated with either cyclosporin or diquafosol and their association with other dry eye markers." (PMID 37354028, 2023). "In summary, we have developed a biocompatible, dual‐functional smart contact lens sensor to monitor IOP and detect MMP‐9 in tears, which were the main risk factors related to glaucoma, dry eye, and others." (PMID 35195359, 2022). "Compared to WT bone marrow chimeras, Pinkie chimeras have increased IL-17+ γδ T cells in the conjunctiva after desiccating stress and anti-IL-17 treatment suppresses dry eye induced corneal MMP-9 production/activity and conjunctival goblet cell loss." (PMID 35402439, 2022). "This study aimed to analyze the association of tear matrix metalloproteinase 9 (MMP-9) immunoassay with the severity of dry eye (DE) signs and symptoms through qualitative, semiquantitative, and quantitative evaluations of immunoassay band." (PMID 34662364, 2021). "Elevation of MMP-9 level is associated with poor epithelial healing, which is also responsible for ocular surface inflammation and dry eye." (PMID 33845799, 2021). "Furthermore, the quantities of the tear MMP-9 assessed by this method were associated with treatment outcomes in patients suffering from dry eye." (PMID 40806027, 2025). "In this study, we only included dry eyes with aqueous deficiency and, therefore, the detection rate of MMP-9 may have been higher compared with previous studies that included both types of dry eye." (PMID 37354028, 2023). "It is thought that the increased MMP-9 expression may cause a more compliant cornea in dry eye, and this hypothesis is supported by our study." (PMID 26634151, 2015). "However, increased MMP-9 levels have been associated with inflamed lacrimal glands in a rabbit dry eye model." (PMID 23977185, 2013). "Hyperosmolarity of dry eye may cause MMP-9 release by the ocular surface cells." (PMID 37354028, 2023). "However, exact mechanism of dry eye development in different underlying conditions is still under investigation, and further studies are required to understand the potential role of tear MMP-9 measurements in lagophthalmic patients." (PMID 36084126, 2022). "This evidence provides the basis for future controlled trials focused on dry eye outcomes and biomarker-driven (e.g., MMP-9) patient selection to explore ACXL as an adjunctive therapy in DED both in children and adults, beyond KC." (PMID 41485028, 2026). "ALA can downregulate the expression of MMP‐2 and MMP‐9 in corneal epithelial cells and activate the antioxidant status of the ocular surface, preventing dry eye;." (PMID 40207422, 2025). "MMP-9 is an inflammatory molecule that participates in the physiological and pathologic mechanisms of dry eye." (PMID 39816208, 2025). "MMP-9 activity and expression are correlated strongly with dry eye symptoms, and an increased expression of this enzyme’s mRNA was found in the posterior conjunctiva of anophthalmic sockets (p < 0.001)." (PMID 41464716, 2025). "Elevated tear levels of IL-6 and MMP-9 have been reported in both KC and dry eye, suggesting shared inflammatory pathways influencing corneal remodeling and tear instability." (PMID 41302278, 2025). "Many studies have demonstrated elevated MMP-9 levels in the tears of individuals suffering from dry eye, which correlate closely with clinical examination findings." (PMID 40076115, 2025). "MMP-9 is a proteolytic enzyme that is involved in wound healing and inflammation, and is known to be involved in dry eye pathogenesis by disrupting the epithelial tight junctions and barrier functions." (PMID 41009673, 2025).
dry eye (continued). "Multiple attempts to reduce dry eye symptoms can be burdensome, and a device facilitating a superior reduction of MMP-9 via a single rinse suggests a potential advantage in terms of patient ease and adherence to treatment." (PMID 39022763, 2024). "In contrast, patients with moderate dry eye accounted for 55.6% of the positive MMP-9 tests, while only 22.5% of individuals with normal tear secretion achieved this status." (PMID 39464763, 2024). "In three out of the 54 control patients (5.6%) and 19 out of the 47 dry eye patients (40.4%), the MMP-9 level in the tear film increased to 40 ng/mL or higher." (PMID 39464763, 2024). "As a result, according to Schirmer’s test, a higher percentage of MMP-9-positive patients had dry eye symptoms that were more severe." (PMID 39464763, 2024). "Elsewhere, the reported prevalence of positive MMP-9 with InflammaDry® ranged from 39% to 50% in dry eye." (PMID 37354028, 2023). "MMP-9 is a molecule strictly related to inflammation, which participates in the physiological and pathologic processes of dry eye." (PMID 37354028, 2023). "MMP-9 is the most important gelatinase present on the ocular surface, and its levels are reported to be higher in the tears of patients with dry eye." (PMID 37354028, 2023). "The increase of MMP-9 activity on the ocular surface can amplify the chronic immune-based inflammation of dry eye." (PMID 37354028, 2023). "Data show that matrix metalloproteinase-9 (MMP-9), a protein hydrolase, on the ocular surface induces inflammatory cytokines and inflammatory responses, playing an important role in dry eye and ocular surface diseases." (PMID 37299596, 2023). "IL-1β has multiple activities in dry eye including stimulating expression of other innate cytokines and chemokines, matrix metalloproteinase-9 (MMP-9) a protease that disrupts corneal barrier function, and IL-17 production by γδT cells." (PMID 37036417, 2023). "We sought to evaluate the expression of matrix metalloproteinase-9 (MMP-9) in dry eyes treated with 0.05% cyclosporin A and 3.0% diquafosol tetrasodium." (PMID 37354028, 2023). "In this study, we compared MMP-9 levels between dry eye patients treated with cyclosporin and diquafosol and demonstrated that MMP-9 expression and the level was lower in eyes treated with cyclosporin as compared with diquafosol." (PMID 37354028, 2023). "Innate inflammatory mediators, such as MMP-9, are important in the pathogenesis of corneal barrier disruption in dry eye." (PMID 37036417, 2023). "Although the mRNA level of matrix metalloprotease (MMP)-2 was comparable, MMP-9 was significantly decreased after the Cact-3 treatment in the dry eye mouse model." (PMID 35563597, 2022). "The dry eye marker MMP-9, cytokines (IL-1β, IL-8), and pain markers (NGF, CGRP) were quantified in tear samples with immunoassays." (PMID 35886858, 2022). "Regarding MMP-9, some studies have reported an increased concentration in vernal keratoconjunctivitis tears and dry eyes." (PMID 35935953, 2022). "In line, studies in experimental dry eye mice found that corticosteroid and doxycycline suppress MMP-9 and inflammatory cytokines expression." (PMID 35886858, 2022). "SuReR also overlapped with MMP9, a widely recognized marker for dry eye syndrome and can disrupt the corneal epithelial barrier and promote corneal neovascularization." (PMID 35277509, 2022). "MMP-9 is an endopeptidase that helps remodel the extracellular matrix and plays a crucial role in dry eye." (PMID 35145982, 2021). "Tear film MMP-9 level is a reliable quantitative index for ocular surface inflammation and tends to increase proportionally with the severity of dry eye." (PMID 33845799, 2021). "An increased concentration and activity of MMP-9 has been observed in the tear fluid of dry eye patients and experimental DED animal models." (PMID 34200187, 2021).
dry eye (continued). "InflammaDry immunoassay is a commercially available tool that has been previously proved effective in evaluating the expression of conjunctival and tears MMP-9, with good sensitivity and specificity in dry eye patients." (PMID 34234963, 2021). "The manufacturers state that the assay requires a tear volume of 10 μl to detect > 40 ng/ml of MMP-9 and is able diagnose dry eye within 10 min." (PMID 32934302, 2020). "The tear matrix metalloproteinase-9 (MMP-9) immunoassay (Inflammadry) exhibits variable results in dry eye (DE) patients." (PMID 32649686, 2020). "Exposure to a desiccating environment increased the perception of dry eye symptoms and concentration of matrix metalloproteinase 9 (MMP‐9) in tears compared to a control environment." (PMID 31997577, 2020). "A previous study examined the utility of the MMP-9 in-situ immunoassay for predicting responses to anti-inflammatory treatments in dry eye patients with confirmed ocular surface inflammation." (PMID 32934302, 2020). "This idea began with the demonstration that matrix metalloproteinase MMP9 is required for damage to the ocular surface in mouse dry eye." (PMID 33374364, 2020). "For these reasons, tear hyperosmolarity and tear MMP-9 point-of-care (POC) tests based on pathological changes in dry eye have attracted attention." (PMID 32934302, 2020). "Treatment with HC eye drops significantly reduced the tear concentrations of TNF-α, IL-8, and MMP-9 vs. vehicle in the ConA dry eye model." (PMID 31680988, 2019). "The suppression of the production of MMP-9 in the ocular surface contributed to the improvement in the corneal barrier function in a model of dry eye mice." (PMID 31003493, 2019). "Long-term dry eye is associated with increased expression of inflammatory factors, such as TNF-α, MMP-2, MMP-9, ICAM-1, and VCAM-1, on the ocular surface." (PMID 30002412, 2018). "Several studies have shown direct association and increased expression levels of inflammatory cytokines IL-6, TNF-α, MCP-1, and MMP-9 in tears of dry eye patients." (PMID 30519584, 2018). "Recent research has evaluated a member of the MMP family, MMP-9, an enzyme produced by corneal epithelial cells, as a biomarker for dry eye." (PMID 28099212, 2017). "Matrix-metalloproteinases (MMPs), specifically MMP-2 (gelatinase A) and MMP-9 (gelatinase B), have certain effects on wound healing, ocular surface disease, dry eye, and keratoconus." (PMID 28280636, 2017). "We postulate that 17β-estradiol upregulates MMP-2 and MMP-9 production in the lacrimal gland and MMP-9 production in the conjunctival epithelium and thus increases the activity of MMP-2 and MMP-9 in tears of dry eye subjects." (PMID 26904272, 2016). "Consistent with previous findings, we also found that the tear concentrations of MMP-2 and MMP-9 in dry eye subjects were significantly higher than those in controls." (PMID 26904272, 2016). "Oxidative stress is one of the initiators in activating the signal transduction pathways (e.g. increased MMP-9 and activation of MAPK pathway) implicated in the breakdown of the integrity and inflammatory response of the ocular surface in experimental dry eye." (PMID 27517861, 2016). "The tear concentrations of MMP-2 and MMP-9 in the dry eye group were significantly greater than those in the control group (P < 0.001)." (PMID 26904272, 2016). "Significantly higher levels of MMP-9 mRNA were observed in dry eye subjects than in normal controls (P = 0.02)." (PMID 26904272, 2016). "Tear MMP-2 and MMP-9 concentrations (P < 0.001), as well as the MMP-9 mRNA expression in conjunctival samples (P = 0.02), were significantly higher in dry eye subjects than in controls." (PMID 26904272, 2016). "MMP9 is the most important gelatinase present on the ocular surface, and its levels seem to be higher in tears of patients with dry eye." (PMID 26221061, 2015).
dry eye (continued). "The MMP-9 activity in the control group was 8.39 +/- 4.70 ng/mL and progressively higher levels of MMP-9 were found in the dry eye groups with the highest levels corresponding to the most severe dry eyes clinically." (PMID 26605353, 2014). "In another study, pro-MMP-9 levels were found to be significantly elevated in various ocular surface diseases: blepharitis (p = 0.013), allergic eye disease, dry eye and conjunctivochalasis (all p < 0.001) compared to controls." (PMID 26605353, 2014). "In a study involving 46 patients with newly diagnosed dry eye and 18 control participants, tear MMP-9 activity was assessed with an MMP-9 activity assay in 1 uL of basal tear fluid." (PMID 26605353, 2014). "Our present study provides convincing evidence that conjunctival explants produced proinflammatory mediators such as IL-1β, TNF-α and MMP-9 in response to air exposure for about 1 week, resembling in vivo dry eye pathophysiology." (PMID 24498087, 2014). "In experimental dry eye, the raised MMP-9 can also be detected in the cornea and lacrimal tissues, implying that tear concentrations were not raised purely due to evaporation." (PMID 26605353, 2014). "The activation of MAPK signaling pathways is known to stimulate the expression of MMP-9 and the production of inflammatory cytokines, which then lead to ocular surface damage and dry eye." (PMID 25580281, 2014). "Matrix-metalloproteinases (MMPs), specifically MMP-2 (gelatinase A) and MMP-9 (gelatinase B), are in tears and also in corneal tissue during wound healing and in ocular surface disease, including dry eye and keratoconus." (PMID 23977185, 2013). "Several studies suggest a relationship between MMP9 expression and dry eye or other ocular diseases, including recurrent corneal melting in patients with primary Sjögren’s syndrome and melted corneal grafts." (PMID 21386923, 2011). "We have previously reported that dry eye stimulates production of metalloproteinase (MMP-9), as well as other MMPs by the ocular surface epithelia." (PMID 22194977, 2011). "Matrix metalloproteinase-9 (MMP-9) is a protease released by the corneal epithelium; increased expression levels compromise the barrier function of the corneal epithelium, and the concentration of MMP-9 in tear fluid corresponds with the clinical manifestations of dry eye." (PMID 40806027, 2025). "Additionally, in various ocular conditions, including moderate to severe dry eyes, the levels of MMP9 enzymes are elevated." (PMID 40076115, 2025). "Indeed, previous studies have shown that patients with post-laser-assisted in situ keratomileusis (LASIK) dry eye display only a 50% positivity rate for MMP-9 with InflammaDry compared to healthy controls." (PMID 40042683, 2025). "In addition, topical application of quercetin was found to significantly reduce MMP-9 levels and improve dry eye ocular surface disorders in a mouse model of dry eye." (PMID 38376774, 2024). "MMP-9 can disrupt the tight junction protein complex, leading to corneal epithelial cell shedding, filamentous keratitis, and an increased likelihood of developing moderate to severe dry eye." (PMID 38956738, 2024). "MMP-9 expression is increased in both gout patients and dry eye patients." (PMID 38376774, 2024). "80% of patients with severe dry eye and 55.6% of moderate dry eye patients were positive for MMP-9." (PMID 39464763, 2024). "Tear matrix metalloproteinase (MMP)-9 is an inflammatory signal in patients with dry eye (DE)." (PMID 38885258, 2024). "Furthermore, a real-time polymerase chain reaction analysis for MMP-9 revealed a discrepancy between dry eye patients with Sjögren’s syndrome and with meibomian gland dysfunction." (PMID 37354028, 2023). "Lower expression of MMP-9 after cyclosporin treatment has implications that reduced T lymphocyte activity by cyclosporin may have downregulated the expression of MMP-9 during the vicious inflammation cycle in dry eye." (PMID 37354028, 2023).